FMR1 (fragile X messenger ribonucleoprotein 1)
Diseases named in the same sentence as FMR1 in open-access papers (continued):
Sharing a sentence is not in itself a finding about the gene and the disease.
fragile X syndrome (continued). "Fragile X syndrome, the most common cause of inherited mental retardation, is caused by the expansion of CGG trinucleotide repeats in the 5′ UTR of the fragile X mental retardation 1 gene (FMR1)." (PMID 24627686, 2014). "We document that retinal function is altered in Fmr1 KO mice, a model of human Fragile X Syndrome." (PMID 25153086, 2014). "Fragile X syndrome (FXS), the most common inherited determinant of intellectual disability and autism spectrum disorders, is caused by loss of the fragile X mental retardation 1 (FMR1) gene product (FMRP), an mRNA-binding translational repressor." (PMID 24046358, 2013). "Thus, while this study does not determine the mechanism behind the aberrant methylation in the expanded FMR1 repeat, it does help refine our mechanistic picture of FMR1 silencing in fragile X syndrome." (PMID 23356558, 2013). "Fragile X syndrome with inherited intellectual disability, including autism, is caused by the inhibition of FMR1 (fragile X mental retardation) gene expression caused by the presence of the triplet (CGG) repeats in the 5′UTR of the FMR1 gene." (PMID 23921685, 2013). "Interestingly, animal models of tuberous sclerosis (Tsc2+/− mice) and fragile X syndrome (Fmr1−/y mice) display abnormal protein synthesis in opposite directions." (PMID 23935565, 2013). "Fragile X syndrome was excluded by molecular analysis of the FMR1 gene." (PMID 23718928, 2013). "LncRNAs may influence the pathogenesis of fragile X syndrome (FXS), which is characterized by a triplet nucleotide repeat expansion in the 5′UTR of FMR1, the gene encoding the neuronal development protein, FMRP." (PMID 24129177, 2013). "Here we report that loss of Fmr1 expression in a mouse model of fragile X syndrome does not cause a change in the number of isolation induced USVs generated by 8 day pups." (PMID 22984567, 2012). "Fragile X syndrome (FXS) is caused by the absence of the mRNA-binding protein Fragile X mental retardation protein (FMRP), encoded by the Fmr1 gene." (PMID 22640474, 2012). "Fragile X syndrome is caused by lack of fragile X mental retardation protein (FMRP) due to silencing of the FMR1 gene." (PMID 22867433, 2012). "In humans, the antisense transcript of FMR1 has an antiapoptotic function and might contribute to fragile X syndrome." (PMID 23285040, 2012). "Interestingly, certain hallmarks of the Fmr1−/− mouse (a model of Fragile X syndrome), including enhanced mGluR-LTD, prolonged epileptiform bursts in hippocampal CA3, and elongated dendritic spines are consistent with the notion of perturbed Ca2+ signaling." (PMID 21935485, 2011). "Children with fragile X syndrome (FXS), an inherited neurodevelopmental disorder, and their mothers with the FMR1 premutation (FXp) both evidence heightened vulnerability for IC deficits, warranting a need for a better understanding of familial IC associations in FMR1 families." (PMID 42131184, 2026). "Mutations in the human FMR1 gene, encoding the Fragile X Messenger Ribonucleoprotein 1 (FMRP), cause the most common monogenic form of ASD, the Fragile X Syndrome (FXS)." (PMID 39604505, 2025). "However, in genetic models such as FMR1-knockout (fragile X syndrome), in which mGluR5 signaling and synaptic protein synthesis are dysregulated, the effects of omega-3 treatment may be different or limited." (PMID 40906373, 2025). "Fragile X syndrome (FXS) is a leading monogenetic cause of intellectual disability and autism spectrum disorders (ASD), resulting from the transcriptional silencing of the FMR1 gene and subsequent loss or reduction in its protein product, fragile x messenger ribonucleoprotein (FMRP)." (PMID 40591708, 2025). "The neurodevelopmental disorder fragile X syndrome (FXS) results from hypermethylation of the FMR1 gene, which prevents production of the FMRP protein." (PMID 40908583, 2025).
fragile X syndrome (continued). "An aspect of almost every fragile X syndrome (FXS) case, the most common form of intellectual disability, is an expansion of 30 CGG repeats in the 5′UTR of FMR1, resulting in transcriptional deactivation and loss of FMRP." (PMID 41516083, 2025). "Fragile X syndrome (FXS) is classified as a genetic disorder located in the fragile X messenger ribonucleoprotein-1 (FMR1) gene on the X chromosome." (PMID 40821284, 2025). "Thus far, ten FSFSs have been identified through sequence mapping to gene-specific expanded (CGG) repeats; the most well-known location being FRAXA, which is found at the fragile X messenger ribonucleoprotein 1 (FMR1) gene and results in fragile X syndrome (FXS)." (PMID 39947477, 2025). "Fragile X syndrome, which is the most common inherited cause of intellectual disability, is associated with the expansion of CGG trinucleotides in the FMR1 gene, and studies have shown that these individuals may exhibit neuropathological changes similar to neurodegenerative diseases." (PMID 41465426, 2025). "Fragile X syndrome (FXS) (OMIM #300624), caused by the transcriptional silencing of the FMR1 gene, represents the most common monogenic cause of autism." (PMID 40869951, 2025). "The silencing of Fmr1 results in a loss of the Fragile X Messenger Ribonucleoprotein (FMRP) and Fragile X Syndrome (FXS)." (PMID 38720271, 2024). "Fragile X syndrome is the most prevalent hereditary cause of mental disability, whose principal hallmark is the dynamic expansion of more than 55–2000 (CGG)n trinucleotide repeats, which are located in the FMR1 gene’s first exon (d(CGG)n) and the 5′-UTR of the FMR1 mRNAs (r(CGG)n)." (PMID 39124893, 2024). "Depending on the clinical presentation, other diagnostic genetic laboratory tests may be considered, including gene repeat expansion analysis, e.g., FMR1 gene for fragile X syndrome, high-resolution chromosome microarray studies, or other laboratory methods including mitochondrial testing." (PMID 38671997, 2024). "Therefore, HDAC inhibitors may offer promising therapeutic interventions in transcriptional activators of the FMR1 gene in such conditions as fragile X syndrome and ASD." (PMID 38672454, 2024). "Fragile X Syndrome (FXS) is a trinucleotide repeat disorder affecting the X chromosome characterized by a cytosine-guanine-guanine (CGG) expansion of the FMR1 gene." (PMID 36816716, 2023). "Decoding of sensory information by downstream regions may be impaired by abnormal activity correlations across areas, which have been observed in Shank3 null macaques and in humans with ASD, and abnormal gamma rhythms, as observed in Fmr1 and Cntnap2 null mice and in people with fragile X syndrome." (PMID 37745660, 2023). "Mutations in the Fragile X Messenger Ribonucleoprotein 1 (FMR1) gene lead to the most common genetic form of intellectual disability and autism, called Fragile X Syndrome (FXS)." (PMID 36909303, 2023). "This protein family, and especially FMR1, is famous for their roles in autism spectrum disorders (ASDs) including the fragile X syndrome (FXS), and related diseases reviewed elsewhere." (PMID 36991279, 2023). "In humans, the expansion and hypermethylation of CGG repeat within the Fmr1 gene, effectively silencing the gene and preventing the expression of the FMRP protein, leading to the Fragile X syndrome (FXS), the most common inheritable form of ASD." (PMID 37238724, 2023).
fragile X syndrome (continued). "Our study also confirmed that the FMR1 KO, which is largely used as a model of Fragile X syndrome, could pinpoint common deregulations and patterns shared among different autism spectrum disorders through the deregulation of autism-related genes and FMRP targets." (PMID 37834379, 2023). "Taken together, analyses performed on neurons from FMR1 KO and FXS patient lines uncovered altered molecular and cellular phenotypes responsible for the neurodevelopmental phenotypes observed in Fragile X syndrome." (PMID 37834379, 2023). "The FMR1 5’UTR CGGexp underlies Fragile X-Associated Disorders, including Fragile X Syndrome (FXS) which is the most common monogenic disorder comorbid with ASD74." (PMID 37645891, 2023). "However, our findings are consistent with other mouse models of ASD including SHANK3 mutants (associated with Phelan-McDermid syndrome) and Fmr1 mutants (associated with Fragile-X Syndrome), which also show no impairment in PPI." (PMID 37649973, 2023). "A typical example is FRAXA, which is responsible for Fragile X syndrome, which is characterized by intellectual and developmental abnormalities due to either the dynamic expansion of a 5′ UTR (CGG)n repeat, or missense and nonsense mutations of the causative FMR1 gene." (PMID 36980839, 2023). "Mutations in the FMR1 gene, encoding the RNA-binding protein FMRP, lead to fragile X syndrome (FXS) and fragile X primary ovarian insufficiency, causes of intellectual disability (ID), autism spectrum disorder (ASD), and premature ovarian failure." (PMID 35731217, 2022). "Fragile X syndrome (OMIM #300624), the major cause of inherited intellectual disability among men, is due to deficiency of the synaptic function regulator FMR1 protein (FMRP; UniProt Q06787), encoded by the FMRP translational regulator 1 (FMR1, OMIM #*309550) gene." (PMID 35641906, 2022). "Moreover, we show that Fmr1 null allele flies, a model of fragile X syndrome, do not exhibit the sudden darkness-induced increase in locomotion." (PMID 36527001, 2022). "For example, fragile X syndrome (FXS), the most common monogenic cause of autism spectrum disorder (ASD), is due to CGG trinucleotide repeat expansion in the FMR1 gene." (PMID 35487213, 2022). "Here we optimized and applied a combined DiIC18-immunolabeling method to characterize the properties of spines in Fmr1 knockout (KO) mice, a pre-clinical model of Fragile X Syndrome (FXS)." (PMID 36359212, 2022). "Although larger trinucleotide expansions give rise to a neurodevelopmental disorder called fragile X syndrome, fragile X-associated tremor/ataxia syndrome (FXTAS) is a late-onset neurodegenerative disorder caused by a “premutation” (55–200 CGG repeats) in the FMR1 gene." (PMID 35207276, 2022). "These atypical behaviors and features remarkably resembled those observed in human patients with Fragile X Syndrome (FXS) and in Fmr1-knockout (KO) mice, which lack normal Fmr1 protein (FMRP)." (PMID 36011319, 2022). "The FM allele is usually accompanied by heterochromatization, transcriptional silencing, and subsequent loss of FMR1 protein (FMRP) expression, resulting in fragile X syndrome (FXS; OMIM #300624)." (PMID 36110216, 2022). "In contrast to FXTAS, those carrying CGG repeats greater than 200 in the FMR1 gene can present with fragile X syndrome (FXS), another neurodegenerative disease that has different clinical features." (PMID 34054431, 2021). "Fragile X syndrome (FXS) is the most common form of inherited intellectual disability and autism caused by the instability of a CGG trinucleotide repeat in exon 1 of the FMR1 gene." (PMID 34946857, 2021). "Thus, female FMR1 mutant offspring could survive in the neonatal stage to analyze the effects of FMRP decrease in higher brain functions related to symptoms of fragile X syndrome." (PMID 34642413, 2021).
fragile X syndrome (continued). "Mutations in the X chromosome gene FMR1, which encodes the fragile X, which encodes the fragile X mental retardation protein (FMRP), cause Fragile X Syndrome (FXS), characterized by intellectual disability, physical features, and behavioral conditions." (PMID 34366796, 2021). "Here we review the utility of genetic testing in patients with neurodevelopmental disorders and describe the three major testing modalities and their yields – chromosomal microarray, exome sequencing (with/without copy number variant calling), and FMR1 CGG repeat analysis for fragile X syndrome." (PMID 33681094, 2021). "Penetrance is incomplete in females with premutation and mutation in FMR1 causing X‐linked dominant fragile X‐associated tremor‐ataxia syndrome (FXTAS; OMIM# 300623) and fragile X syndrome (FXS; OMIM# 300624), respectively." (PMID 33816657, 2021). "This SSR was adjacent to the promoter and affected the performance of the FMR1 gene, leading to fragile X syndrome (FXS)." (PMID 35052439, 2021). "The Fragile X-related disorders (FXDs), which include the intellectual disability fragile X syndrome (FXS), are disorders caused by expansion of a CGG-repeat tract in the 5′ UTR of the X-linked FMR1 gene." (PMID 34681027, 2021). "Fragile X syndrome (FXS) is a hereditary neurodevelopmental disability that results from an abnormal expansion of the CGG trinucleotide repeat in the FMR1 gene on the X chromosome." (PMID 33299404, 2020). "The FMR1 gene is the gene responsible for Fragile X Syndrome (FXS) affecting ~1/3,717 to 1/8,918 Caucasian males." (PMID 32766278, 2020). "Fragile X syndrome (FXS) is a single gene disorder that results in the silencing of Fmr1, and has considerable overlap in symptomology with ASD and has been linked to 5-HT dysregulation." (PMID 32581705, 2020). "Fragile X syndrome (FXS) is a developmental disorder resulting from an expansion of a CGG repeat sequence in the Fragile X Mental Retardation Gene (FMR1) on the X chromosome." (PMID 32260354, 2020). "The normal number of CGG of FMR1 is less than 45 CGG repeats in the 5′ UTR region,gray zone contains 46–54 repeats (carriers with either movement disorders or memory complaints), premutation contains 55–200 repeats (causes FXTAS or FXPOI) and full mutation > 200(causes Fragile X syndrome)." (PMID 32312236, 2020). "In fragile X syndrome (FXS), expansion of a CGG repeat tract in the 5′-untranslated region of the FMR1 gene to >200 repeats causes transcriptional silencing by inducing heterochromatin formation." (PMID 32230785, 2020). "Fragile X syndrome, the most common inherited form of intellectual disability, is caused by the CGG trinucleotide expansion in the 5’-untranslated region of the Fmr1 gene on the X chromosome, which silences the expression of the fragile X mental retardation protein (FMRP)." (PMID 31112584, 2019). "Specific RNAs bound by FMR1 are downregulated in Fmr1 knockout mice, implying FMR1 could not only silence gene expression but also stabilize its targets FMR1 is most well known for its role in Fragile X syndrome also due to a triplet repeat expansion in the 5’ untranslated region of the FMR1 gene." (PMID 31593562, 2019). "Fragile X syndrome (FXS) is an autism spectrum disorder arising from increased repeats of CGG trinucleotide in the FMR1 gene." (PMID 31685673, 2019).
fragile X syndrome (continued). "Fragile X syndrome (FXS) is the most common inherited form of intellectual disability, caused by a region of expanded CGG trinucleotide repeats in FMR1 (OMIM accession number: 309550) on the X chromosome." (PMID 31694075, 2019). "Fragile X syndrome (FXS) is the most common heritable form of intellectual disability and ASD, which is caused due to the silencing of FMR1." (PMID 31202261, 2019). "Fragile X syndrome (FXS) is caused by a mutation in the FMR1 gene on the X chromosome, leading to decreased levels of FMR1 protein (FMRP), which causes the array of neuropsychological impairments that define FXS." (PMID 29925305, 2018). "If the repeat length extends over 200 (full mutation: FM), individuals can develop the fragile X syndrome (OMIM accession number: 300624), which is linked with a mental retardation caused by FMR1 gene silencing and loss of fragile X mental retardation 1 protein (FMRP)." (PMID 29981579, 2018). "Epigenetic silencing of FMR1 gene expression leads to the development of Fragile X syndrome (FXS) that is characterized by intellectual disability and other behavioral problems including autism." (PMID 29218006, 2017). "Patients with the Fragile X Syndrome (FXS) carry a triplet repeat expansion in the FMR1 gene that lead to reduced translation of the FMRP protein." (PMID 28979198, 2017). "mGluR-LTD has been widely studied in relation to the neurodevelopmental disorder fragile X syndrome (FXS) and shown to be enhanced in hippocampal slices from Fmr1 KO mice, a mouse model of FXS." (PMID 29173281, 2017). "Fragile X syndrome (FXS), a common cause of intellectual disability and autism, results from the expansion of a CGG-repeat tract in the 5′ untranslated region of the FMR1 gene to >200 repeats." (PMID 27713816, 2016). "Examples of ASDs caused by gene mutations include fragile X syndrome (FXS) and tuberous sclerosis (TSC) which have mutations in the FMR1 and TSC1/2 genes, respectively." (PMID 26594141, 2015). "Fragile X syndrome (FXS) develops from excessive trinucleotide CGG repeats in the 5’-untranslated region at Xq27.3 of the Fmr-1 gene, which functionally silences its expression and prevents transcription of its protein." (PMID 26580204, 2015). "It has been shown that 5-HT7 receptor (agonist 8-OH-DPAT) activation could reverse mGluR-induced AMPA receptor internalization and correct excessive mGluR-LTD in hippocampal neurons of Fmr1 knockout mice, suggesting that 5-HT receptors may represent a novel therapeutic target for fragile X syndrome." (PMID 25767435, 2015). "In a previous work, we have shown that 5-HT, through activation of 5-HT7 receptors, is able to reverse exaggerated mGluR-LTD in the Fmr1 KO mouse model of Fragile X Syndrome (FXS)." (PMID 25814945, 2015). "Fragile X syndrome (FXS) is the most common heritable form of intellectual disability and is caused by an expansion of a CGG trinucleotide repeat tract in the 5' UTR of the FMR1 gene on the X chromosome." (PMID 25278957, 2014). "One example using FX-iPSCs to model Fragile X syndrome is a study aimed to evaluate the reactivation of FMR1 in FXS-iPSCs and their neuronal derivatives through epigenetic modulation drugs." (PMID 26237596, 2014). "Fragile X syndrome (FXS) is the most common single gene cause of intellectual disability and it is characterized by a CGG expansion of more than 200 repeats in the FMR1 gene, leading to methylation of the promoter and gene silencing." (PMID 25436181, 2014). "Interestingly, we found that 5-HT7 receptor activation reversed mGluR-mediated endocytosis of AMPA receptors and mGluR-LTD also in Fmr1 KO mice, a mouse model of Fragile X Syndrome, the most common form of inherited intellectual disability associated with epilepsy and autism." (PMID 25221471, 2014).